CCN6 (cellular communication network factor 6)
Diseases named in the same sentence as CCN6 in open-access papers (continued):
Sharing a sentence is not in itself a finding about the gene and the disease.
breast carcinoma (continued). "Immunohistochemical analysis showed that when present, CCN6 protein was predominantly cytoplasmic and that NICD1 protein was localized to the nuclei of breast cancer cells." (PMID 26933820, 2016). "Conversely, when present, CCN6 protein binds to BMP4 and inhibits the BMP4-mediated activation of MAP3K7/MAPK14 kinases and decreases the invasiveness of breast cancer cells." (PMID 26395334, 2015). "Clinical samples confirm a correlation between low CCN6 and high IMP2 in spindle and squamous MBC, highlighting a CCN6/IMP2 axis with therapeutic implications and illustrating the diverse mechanisms through which IMP2 contributes to breast cancer progression." (PMID 40141058, 2025). "Similar to findings obtained with 4T1 cells, knockdown of OTUB1 significantly reduced CCN6 protein levels in these human breast cancer cells, but did not influence mRNA levels of CCN6." (PMID 37608493, 2023). "Moreover, it was also shown that CCN6 decreases EMT and invasion by attenuating IGF-1 receptor signaling in breast cancer." (PMID 37590989, 2023). "Ccn6/Wisp3 knockdown up-regulated the expression of IGF2BP2 in mice, who developed mammary carcinomas characterized by spindle and squamous differentiation, validated hallmarks of metaplastic breast carcinomas." (PMID 33568150, 2021). "CCN1, CCN2, CCN3, and CCN4 are pro-tumorigenic and may be responsible for human breast carcinoma; while CCN1, CCN3, CCN5 and CCN6 have anti-tumorigenic effects." (PMID 34940056, 2021). "The pro-tumorigenic CCN1, CCN2, CCN3, and CCN4 may lead to human breast cancer, although the anti-tumorigenic actions of CCN5 and CCN6 are also present." (PMID 34940056, 2021). "Similar to human aggressive breast carcinomas, MDA-MB-231 and -436 cells exhibit low CCN6 protein." (PMID 26933820, 2016). "In the present study we demonstrate that ectopic CCN6 overexpression in MDA-MB-231 and MDA-MB-436 aggressive TN breast cancer cells induces a mesenchymal to epithelial transition (MET), reduces cancer cell migration and invasion, and is sufficient to decrease TICs, tumor initiation, and metastasis." (PMID 26933820, 2016). "Recently, Lorenzatti and colleagues found that CCN6, a tumor inhibitory protein, could suppress the expression of EMT transcriptional factor ZEB1 in breast cancer cells through attenuation of IGF-1R signaling." (PMID 23663564, 2013). "Therefore, we hypothesized that CCN6 antagonized BMP signaling via binding to BMP2, as was observed in breast cancer cells." (PMID 37590989, 2023).
progressive pseudorheumatoid dysplasia (12 papers, 2007 to 2025). "In fact, mutations in the CCN6 gene, which span across the entire length of the protein coding sequence, are linked with a musculoskeletal disorder termed progressive pseudorheumatoid dysplasia (PPRD)." (PMID 33644064, 2021). "Progressive pseudorheumatoid dysplasia (PPD) is a rare autosomal recessive cartilage disorder caused by biallelic variants in CCN6, which encodes the matricellular protein WISP3." (PMID 41009407, 2025). "Mutations in the CCN6 (WISP3) gene are linked with a debilitating musculoskeletal disorder, termed progressive pseudorheumatoid dysplasia (PPRD)." (PMID 33644064, 2021).
inflammatory breast carcinoma (9 papers, 2005 to 2026). An advanced, invasive breast adenocarcinoma characterized by the presence of distinct changes in the overlying skin. "In spite of the weak IGF binding, CCN6 is implicated in inflammatory breast cancer as knock down leads to IGF1 induced tumorigenesis and cell growth, and CCN6 is lost in more than 80% of inflammatory breast cancers." (PMID 37245184, 2023). "Our group has previously reported that CCN6 loss is associated with a highly metastatic form of invasive breast carcinoma, termed inflammatory breast cancer, as well as with non-inflammatory invasive breast cancers with lymph node metastasis." (PMID 26933820, 2016). "CCN6 (WISP3) is a secreted matrix-associated protein (36.9 kDa) of the CCN family (named after CTGF, Cyr61 and Nov) that is reduced or lost in invasive carcinomas of the breast with lymph node metastasis and in inflammatory breast cancer." (PMID 26933820, 2016). "These functions of CCN6 may explain at least in part the enhanced metastasis observed in inflammatory breast cancer and in invasive carcinomas with low or absent CCN6 expression." (PMID 26933820, 2016).
chondrosarcoma (7 papers, 2016 to 2023). A malignant cartilaginous matrix-producing mesenchymal neoplasm arising from the bone and soft tissue. "Using the Transwell assay, we found that CCN6 dose-dependently stimulated the migratory and invasion activity of human chondrosarcoma cells." (PMID 30237403, 2018). "We show how CCN6 promotes chondrosarcoma cell migration and invasion via matrix metallopeptidase-9 (MMP)-9 expression." (PMID 30237403, 2018). "When we transfected chondrosarcoma cells with κB-luciferase, we found that CCN6 enhanced NF-κB activity." (PMID 30237403, 2018). "Our previous work indicates that CCN6 regulates metastasis in chondrosarcoma, enhancing chondrosarcoma cell migration by increasing levels of ICAM-1 expression." (PMID 30237403, 2018). "In this current study, stimulation of chondrosarcoma cell lines with CCN6 promoted cell motility and MMP-9 expression, which in turn activated the PI3K/Akt/mTOR/NF-κB signaling pathway." (PMID 30237403, 2018). "Our findings demonstrate CCN6-induced enhancement of MMP-9 expression and secretion in human chondrosarcoma cells; the loss of MMP-9 expression significantly suppressed CCN6-induced cell migration and invasion activity." (PMID 30237403, 2018). "Our experimental data have shown that CCN6 enhances the wound-healing migration of chondrosarcoma cells by increasing ICAM-1 expression." (PMID 30237403, 2018). "This study emphasizes the importance of CCN6 in chondrosarcoma metastasis and suggests that CCN6 can be a useful target in the management of chondrosarcoma." (PMID 30237403, 2018). "CCN6 increased migration of chondrosarcoma cells, which was prevented by anti-αvβ3 and αvβ5 integrin monoclonal antibodies, mitogen-activated protein kinase (MEK) inhibitors." (PMID 26933820, 2016). "CCN6 appears to be a promising therapeutic target in chondrosarcoma metastasis." (PMID 30237403, 2018). "We examined whether NF-κB activation plays a role in CCN6-induced activation of the signaling transduction pathway and subsequent chondrosarcoma cell migration, invasion, and enhanced MMP-9 expression." (PMID 30237403, 2018). "Upregulation of CCN6 expression promotes metastasis in chondrosarcoma." (PMID 30237403, 2018). "We hypothesized that any of these MMPs might be involved in CCN6-directed chondrosarcoma migration and invasion activity." (PMID 30237403, 2018). "We hypothesized that CCN6 would influence metastasis in chondrosarcoma cells." (PMID 30237403, 2018). "CCN6 may therefore be a novel target for chondrosarcoma metastasis." (PMID 30237403, 2018). "It is unknown as to whether CCN6 affects human chondrosarcoma metastasis." (PMID 30237403, 2018). "Importantly, CCN6 knockdown profoundly inhibited chondrosarcoma cell metastasis to lung." (PMID 30237403, 2018). "CCN6 appears to depend upon activation of the PI3K, Akt, and mTOR signaling pathways to induce NF-κB activation in human chondrosarcoma cells." (PMID 30237403, 2018). "We also found that mTOR phosphorylation in chondrosarcoma cells was increased after CCN6 treatment, while incubation of cells with PI3K or Akt inhibitors antagonized CCN6-induced mTOR phosphorylation." (PMID 30237403, 2018). "It appears that CCN6 acts via the PI3K/Akt-dependent signaling pathway to enhance MMP-9 mRNA expression, cell migration, and invasion of human chondrosarcoma cells." (PMID 30237403, 2018). "In this current study, we explored the role of CCN6 in metastasis and upregulation of MMP-9 in human chondrosarcoma cells." (PMID 30237403, 2018). "This suggests that CCN6 increases MMP-9 expression and induces cell metastasis in human chondrosarcoma cells via the PI3K/Akt/mTOR/NF-κB signaling pathway." (PMID 30237403, 2018). "Our findings reveal an important mechanism underlying CCN6-induced metastasis and they highlight the clinical significance between CCN6 and MMP-9 in regard to human chondrosarcoma." (PMID 30237403, 2018).
chondrosarcoma (continued). "Our results indicate that endogenous CCN6 activates the PI3K/Akt/mTOR/NF-κB signaling pathway and augments MMP-9-dependent lung metastasis of chondrosarcoma in vivo." (PMID 30237403, 2018). "Our data show that NF-κB activation plays an important part in CCN6-induced migration and MMP-9 expression in human chondrosarcoma cells and that blocking the NF-κB-dependent signaling pathway inhibits CCN6-induced MMP-9 expression and cancer metastasis." (PMID 30237403, 2018). "This indicates that the PI3K/Akt/mTOR signaling pathway is required for CCN6-induced MMP-9 expression and chondrosarcoma cell metastasis." (PMID 30237403, 2018). "Pretreating chondrosarcoma cells with PI3K inhibitors (Ly294002, wortmannin) or siRNAs abolished CCN6-mediated cell migration, invasion, and MMP-9 mRNA expression, while transfection of cells with p85 or Akt siRNAs inhibited p85 and Akt expression." (PMID 30237403, 2018). "Thus, the PI3K/Akt/mTOR signaling pathway must be activated for CCN6-induced enhancement of cell migration, invasion, and MMP-9 production in human chondrosarcoma cells." (PMID 30237403, 2018). "In addition, we observed a strong correlation between CCN6 and MMP-9 expression in human chondrosarcoma tissue and preclinical analyses." (PMID 30237403, 2018).
gastric cancer (7 papers, 2016 to 2023). A primary or metastatic malignant neoplasm involving the stomach. "Differential expression analysis showed that IGFBP7, CCN2, ESM1, CCN4 and CCN6 mRNA were over-expressed in gastric cancer tissues while CCN5 mRNA was down-expressed (all p < 0.05)." (PMID 37304887, 2023). "For example, the knockdown of CCN6 expression suppressed gastric cancer cell proliferation and migration via the Wnt/β-catenin signaling pathway in an in vitro investigation, and high CCN6 expression has been linked to poor prognosis in patients with gastric cancer." (PMID 30237403, 2018).
osteoarthritis (4 papers, 2006 to 2023). A noninflammatory degenerative joint disease occurring chiefly in older persons, characterized by degeneration of the articular cartilage, hypertrophy of bone at the margins and changes in the synovial membrane. "Regarding human skeletal disorders, more than 20 mutations in CCN6 have so far been identified in patients with progressive pseudorheumatoid dysplasia, which is a genetic bone disorder characterized by severe osteoarthritis and osteopenia of spine." (PMID 37590989, 2023). "Studies have highlighted that expression of CCN6 is higher in RA synovium and fibroblast-like synoviocytes compared with osteoarthritis and normal synovial tissue." (PMID 38268722, 2023).
bladder cancer (3 papers, 2016 to 2019). "Downregulation of CCN6 using siRNAs reduced cell proliferation and induced apoptosis in bladder cancer cells in vitro." (PMID 26933820, 2016).
Nephroblastoma (3 papers, 2021 to 2022). An embryonal neoplasm characterized by the presence of epithelial, mesenchymal, and blastema components. "The CCN family includes CCN1/CYR61 (cystein-rich 61], CCN2/CTGF (connective tissue growth factor), CCN3/NOV (nephroblastoma overexpressed), and also CCN4/WISP-1, CCN5/WISP-2, CCN6/WISP-3 (Wnt-inducible secreted proteins)." (PMID 34940056, 2021).
breast tumor (2 papers, 2016 to 2023). "Malignant tumours had lower levels of OTUB1 and CCN6 than did benign tumours and normal breast tissues, and the levels of OTUB1 were positively correlated with CCN6 levels in breast tumours." (PMID 37608493, 2023). "Deletion of OTUB1, accompanied by reduced CCN6 protein abundance, enhanced the growth of 4T1 cells in vitro and in vivo, and the effect of OTUB1 deletion was abolished by CCN6 overexpression, unambiguously showing that OTUB1 inhibits breast tumour via stabilizing CCN6." (PMID 37608493, 2023).
invasive breast carcinoma (2 papers, 2016 to 2019). A carcinoma that infiltrates the breast parenchyma. "We found a novel significant association between CCN6 and NICD1 protein expression in invasive carcinomas of the breast." (PMID 26933820, 2016).
metaplastic carcinomas of the breast (2 papers, 2009 to 2021). "In addition, IGF2BP2 was regulated by CCN6 protein in metaplastic carcinomas of the breast." (PMID 34608837, 2021).
oral cancer (2 papers, 2019 to 2023). "Our data provide evidence that CCN6 could be a therapeutic target for the development of treatments to suppress the settlement and invasion of oral cancer cells in the jawbone." (PMID 37590989, 2023). "Considering that ID3 expression, which is a target gene of both Smad1/5/9 and p38, was increased by CCN6 combined with BMP2, and that production of CCN6 and BMP2 increased in the cells before EMT, it is suggested that CCN6 combined with BMP2 suppresses EMT of oral cancer cells in primary lesions." (PMID 37590989, 2023). "In contrast, CCN6 did not affect EMT in epidermoid carcinoma A431 cells, which are not oral cancer cells, stimulated by TGF-β." (PMID 37590989, 2023).
benign breast tumours (1 paper, 2023). "By contrast, benign breast tumours and adjacent breast tissues showed comparable protein expression of OTUB1 and CCN6." (PMID 37608493, 2023).
diabetes (1 paper, 2023). "Prior research has delved into the association of various members of the CCN family (ranging from CCN1 to CCN6) with metabolic disorders, encompassing conditions such as obesity, diabetes, insulin resistance, and non-alcoholic fatty liver." (PMID 37919772, 2023).
ovarian tumour (1 paper, 2023). "In the screening experiment, we found that overexpression of OTUB1, a DUB of the ovarian tumour proteases (OTU) subfamily, markedly increased the protein abundance of CCN6 in 4T1 cells." (PMID 37608493, 2023).
tumor (37 papers, 2005 to 2026). "In line with in vitro findings, OTUB1‐deficient allografted tumours had reduced levels of CCN6." (PMID 37608493, 2023). "Loss of CCN6 in mammary-specific knockout mice leads to upregulation of IMP2 and increased tumor aggressiveness, while restoring CCN6 reduces IMP2 levels and tumor growth." (PMID 40141058, 2025). "Although the tumour‐suppressive function of CCN6 has been extensively studied, molecular mechanisms regulating protein levels of CCN6 remain largely unclear." (PMID 37608493, 2023). "Compared with control, the OTUB1−/− group showed significantly increased tumour volume, while the tumour volume was significantly reduced in the OTUB1−/− + CCN6 group." (PMID 37608493, 2023). "Membrane staining of CCN4, CCN5 and CCN6 were reduced in CRC tumours, with an elevated cytoplasmic staining of CCN4 and CCN6 but not CCN5." (PMID 28412738, 2017). "CCN6 overexpression in the breast TIC population significantly delayed tumor development, reduced tumor volume, and blocked the development of spontaneous metastasis." (PMID 26933820, 2016). "In vivo, CCN6 overexpression in the TIC population of MDA-MB-231 cells delayed tumor initiation, reduced tumor volume, and inhibited the development of metastasis." (PMID 26933820, 2016). "CCN6 overexpression significantly delayed tumor onset, decreased tumor volume, and blocked distant metastasis of ALDH1+ MDA-MB-231 cells compared with controls (Kaplan-Meier, log-rank P < 0.05)." (PMID 26933820, 2016). "Except CCN6, the expression of CCNs were significantly different between tumor and normal." (PMID 36589241, 2022). "This subtype classification additionally underscores heterogeneity of MpBC tumor development and further need for multiple MpBC mouse models, as down-regulation of CCN6 and cellular metabolism and protein translation up-regulation are not significant in our epigenetic-driven model." (PMID 34508101, 2021). "At 8 weeks, IVIS findings showed that knockdown CCN6 reduced tumor metastasis to the lung." (PMID 30237403, 2018). "However, many studies reported that CCN6 can serve as both a tumor suppressor and promoter." (PMID 33833779, 2021). "Finally, CCN6 is considered a tumour suppressor for breast cancer." (PMID 32081971, 2020). "Thus, CCN6 molecular mechanisms appear to differ between different types of tumor cells." (PMID 30237403, 2018). "Our laboratory has successfully delivered CRISPR–dCas9 systemically into MCF7 xenografts using dendritic polymers to reactivate the tumor suppressor genes MASPIN and CCN6 in the tumor site, leading to potent and long-lasting cancer growth inhibition." (PMID 31636382, 2020). "Wnt1‐inducible signalling pathway protein 3 (WISP3/CCN6) belongs to the CCN (CYR61/CTGF/NOV) family of proteins, dysregulation of this family contributed to the tumorigenicity of various tumours." (PMID 30793395, 2019). "Our previous study has shown confined staining of CCN4, CCN5 and CCN6 at the cell membrane in normal colorectal epithelial cells, while an increased staining of CCN4 and CCN6 was seen in CRC tumours." (PMID 28412738, 2017). "CCN6 is also acts as a tumor suppressor in HCC by negative regulation of β-catenin/TCF/LEF signaling." (PMID 33833779, 2021). "CCN6 has received much attention in the last few years due to its involvement in many cancer-related processes, including EMT, cell death, invasion, and metastasis, and its function as a tumor suppressor." (PMID 33833779, 2021). "Finally, work in our group has demonstrated tumor suppression and regression through the reactivation of silenced tumor suppressor genes MASPIN and CCN6 in an MCF7 xenograft mouse model of breast cancer." (PMID 34988459, 2021). "CCN6 and NICD1 were scored as high when over 10% of the cancer cells showed moderate or strong staining and were scored as low when staining was present in less than 10% of tumor cells." (PMID 26933820, 2016).
tumor (continued). "In addition, induction of CCN1/Cyr61 and CCN5/WISP2 was also found in the CCA tumors, whereas CCN3/NOV and CCN6/WISP3 did not have obvious changes in both the nontumor and tumor samples from the CCA tissues." (PMID 27829832, 2016). "Except for CCN5 and CCN6, which have not been studied in this context, all CCN protein family members have been associated with hematologic malignancies and often, but not always, their expression is increased in either tumor cells or in stromal cells, mostly displaying pro-tumor effects." (PMID 33428075, 2021).